SIRT6 (sirtuin 6)
Diseases named in the same sentence as SIRT6 in open-access papers (continued):
Sharing a sentence is not in itself a finding about the gene and the disease.
cardiac hypertrophy (continued). "In the context of cardiovascular diseases, SIRT6 was shown to act as a protective factor against cardiac hypertrophy in both in vitro and in vivo experiments, and it does so through multiple mechanisms." (PMID 39215785, 2025). "Nevertheless, the interaction between SIRT6 and Nrf-2-mediated mitochondrial biogenesis in the context of doxorubicin-induced HF and myocardial hypertrophy remains inadequately understood." (PMID 40093797, 2025). "Treatment with SIRT6 transgenic intervention effectively restored normal cardiac ejection function, alleviated myocardial hypertrophy and inflammation, and inhibited pyroptosis." (PMID 40093797, 2025). "Limonin can also inhibit the ubiquitination and degradation of SIRT6, stabilize the level of SIRT6 protein, promote its expression, reduce cardiac hypertrophy, and improve cardiac function." (PMID 39944619, 2025). "Sirt6 prevents the heart from experiencing age-induced cardiac hypertrophy and fibrosis by controlling a number of cellular processes linked to aging." (PMID 41567643, 2025). "Relevant studies confirm that Sirt6 activation enhances autophagic flux by preventing the accumulation of autophagy‐related factors and ameliorates cardiac hypertrophy via inhibition of the Akt/FoxO3 pathway, which promotes autophagy." (PMID 41466491, 2025). "More research efforts are needed to deeply investigate regulatory effects of Sirt6 in cardiac hypertrophy." (PMID 37497437, 2023). "SIRT6 has been shown to regulate various signalling pathways such as myocardial hypertrophy, inflammatory injury and myocardial remodelling." (PMID 37603612, 2023). "Mice with heart‐specific knockout of SIRT6 spontaneously develop cardiac hypertrophy and heart failure, while SIRT6 transgenic overexpression blocks pressure overload and agonist‐induced myocardial hypertrophy." (PMID 37603612, 2023). "SIRT6 is a H3K9ac deacetylase, and our previous study showed that H3K9ac acetylation levels increased in mouse cardiac hypertrophy." (PMID 37603612, 2023). "SIRT6 expression is downregulated in human heart failure, indicating that SIRT6 is involved in the pathogenesis of cardiac hypertrophy and heart failure." (PMID 37008337, 2023). "Consistently, SIRT6 KO mice develop cardiac hypertrophy and heart failure at around 8–12 weeks of age." (PMID 36901738, 2023). "SIRT3 has also been studied in the heart and shown to protect against both cardiac hypertrophy and I/R injury, while SIRT6 KO mice exhibit cardiac hypertrophy." (PMID 37728319, 2023). "Such Sirt6 half-depletion mouse models developed cardiac hypertrophy, whereas mouse models overexpressing Sirt6 displayed significant attenuation of cardiac hypertrophy." (PMID 37497437, 2023). "Increasing evidence has demonstrated that SIRT6 functions as a negative regulator of cardiac hypertrophy." (PMID 37603612, 2023). "The USP10 attenuates aortic constriction-induced cardiac hypertrophy by directly regulating Sirt6 levels (Zhang DH." (PMID 37497437, 2023). "SIRT6 affects the pathogenesis of various cardiovascular diseases by regulating cardiac hypertrophy, inflammatory, and oxidative stress." (PMID 35224092, 2022). "For example, Sirtuin-6 (SIRT6) is involved in cardioprotection including cardiac hypertrophy and heart failure." (PMID 34831061, 2021). "We have previously demonstrated that Sirt6 blocks the pressure overload-induced cardiac hypertrophy in mice." (PMID 33934090, 2021). "Sirt6.Tg mice showed reduced cardiac hypertrophy, as measured by a decreased HW/TL ratio and mRNA levels for βMHC and ANF, compared to non-transgenic wild-type controls." (PMID 33934090, 2021). "Taken together these data establish a critical connection between SIRT6, mTOR signaling, protein synthesis and cardiac hypertrophy." (PMID 33855020, 2021). "Here, we show that Sirt6 can also mitigate aging-induced cardiomyocyte senescence and cardiac hypertrophy." (PMID 33934090, 2021).
cardiac hypertrophy (continued). "Overexpression of Nmnat2 promotes the activation of SIRT6 and blocks angiotensin II-induced cardiac hypertrophy." (PMID 33855020, 2021). "Analogously, SIRT6 (sirtuin 6) is a preautophagy histone deacetylase that function in stress response, and SIRT6-/- mice are characterized by cardiac hypertrophy and heart failure." (PMID 34341709, 2021). "Overexpressed SIRT6 attenuates PE-induced cardiac hypertrophy through reduction of p300 by proteosomal degradation." (PMID 34831061, 2021). "Angiotensin-II induced cardiac hypertrophy is blocked by over-expression of nicotinamide mononucleotide adenylyltransferase-II (Nmnat-II) that is responsible for activation of Sirt6." (PMID 33442387, 2020). "SIRT6 also suppresses isoproterenol (ISO)-induced cardiac hypertrophy through the activation of autophagy." (PMID 31492861, 2019). "We have previously reported that cardiac-specific SIRT6-KO mice develop cardiac hypertrophy in an age-dependent manner." (PMID 31372634, 2019). "SIRT6 is another important mammalian sirtuin protein that appears to protect against cardiac hypertrophy." (PMID 31492861, 2019). "Taken together these data establish a critical connection between SIRT6, mTOR signalling, protein synthesis and cardiac hypertrophy." (PMID 31372634, 2019). "Since reduced autophagy was seen to contribute towards the pathogenesis of cardiac hypertrophy, it was demonstrated in this study that the increase in the levels of SIRT6 lead to an enhanced autophagy of cardiomyocytes." (PMID 29966233, 2018). "SIRT6 was shown to have protective effects against cardiac hypertrophy with the onset of autophagy by promoting the transcription factor FOXO1 (also plays a role in gluconeogenesis)." (PMID 29966233, 2018). "Previous studies in our laboratory and others have revealed that SIRT6 can prevent and inhibit cardiac hypertrophy." (PMID 30670969, 2018). "On the other hand, in a condition of Sirt6 deficiency, the hyper-acetylation of H3K9 increases c-Jun activity and cardiac hypertrophy worsening heart failure." (PMID 30304806, 2018). "Researchers have also identified results that highlight the importance of SIRT6 in cardiac failure and hypertrophy." (PMID 29966233, 2018). "It has been shown, in fact, that Sirt6 overexpression protects against cardiac hypertrophy by physical interaction with c-Jun, which becomes inactivated and the transcription of genes involved in IGF signaling is inhibited." (PMID 30304806, 2018). "SIRT6 prevents cardiac hypertrophy and heart failure, and it contributes to the maintenance of endothelial homeostasis, thus delaying vascular aging." (PMID 28659816, 2017). "Similar to SIRT3, SIRT6 knockdown mice showed cardiac hypertrophy and the overexpression of SIRT6 rescues cardiac hypertrophy." (PMID 28197299, 2017). "Previous studies have shown that Sirt6 can act as a negative regulator of cardiac hypertrophy, which is also indicative of its potential cardioprotective effect." (PMID 28582407, 2017). "SIRT6-mutant mice spontaneously developed concentric cardiac hypertrophy with significantly increased HW/BW ratio, reduced left ventricular internal diameter, reduced fractional shortening as well as increased cardiomyocyte size and interstitial fibrosis." (PMID 29069788, 2017). "In a previous study, we have reported hyper-phosphorylation of Akt and induction of cardiac hypertrophy in SIRT6-KO mice." (PMID 28928419, 2017). "Both single- and double-SIRT6 knockout mice develop significant cardiac hypertrophy, fibrosis and dysfunction." (PMID 29069788, 2017). "SIRT6 extends lifespan in male mice or prevents cardiac hypertrophy via the attenuation of IGF-AKT pathways." (PMID 26983852, 2016). "SIRT6 plays an important role in genomic stability, DNA repair, metabolic homeostasis and diseases such as obesity, cardiac hypertrophy and cancer." (PMID 26983852, 2016).
cardiac hypertrophy (continued). "SIRT6 deficiency was reported to induce hyperactivation of IGF-Akt signaling, which culminates in the development of cardiac hypertrophy and heart failure in mice." (PMID 26732053, 2016). "SIRT6 deficiency leads to an elevated H3K9 acetylation level and enhanced interaction with the stress-responsive transcription factor c-Jun, further promoting IGF signaling and ultimately leading to cardiac hypertrophy." (PMID 40710369, 2025). "In addition, SIRT2 and SIRT6 have also been shown to prevent cardiac hypertrophy, during which the IGF-AKT signaling pathway is continuously activated." (PMID 40710369, 2025). "Finally, SIRT6 inhibits the development of cardiac hypertrophy and heart failure by deacetylating H3K9 and repressing the transcriptional activity of c‐Jun and IGF/Akt signaling." (PMID 39215785, 2025). "Additionally, USP10 functions as a Sirt6 deubiquitinase to promote tumorigenesis and cardiac myocyte hypertrophy." (PMID 39430239, 2024). "The loss of Sirt6 in knockout mice led to increased H3K9 acetylation, allowing stress-responsive transcription factor c-Jun to interact more easily, activating the IGF-AKT signalling pathway, which resulted in cardiac hypertrophy." (PMID 39596076, 2024). "Besides, Sirt6, depending on its deacetylase activity, represses the expression of nuclear factor of activated T cells c4 (NFATc4) and protects against cardiac hypertrophy." (PMID 37497437, 2023). "Interestingly, on the contrary, overexpression of Sirt6 in rat cardiomyocytes significantly dampens hypertrophic responses, which again manifested that Sirt6 plays crucial roles in regulating cardiac hypertrophy pathogenesis." (PMID 37497437, 2023). "It claimed that cardiac-specific deletion of Sirt6 notably thickens ventricular walls, increases cardiac interstitial fibrosis, and exacerbates cardiac hypertrophy; whereas Sirt6 overexpression mitigates pressure-overload-induced cardiac hypertrophy." (PMID 37497437, 2023). "Recent studies have demonstrated regulatory effects of Sirt6 on cardiac hypertrophy." (PMID 37497437, 2023). "Up until now, nobody has identified a deleterious role of Sirt6 regarding cardiac hypertrophy." (PMID 37497437, 2023). "Similarly, a new PARP-1 inhibitor, AG-690/11026014 (6014), has been revealed to retard AngII-induced cardiac hypertrophy, partly because of the activation of Sirt6 by elevating intracellular NAD + levels." (PMID 37497437, 2023). "SIRT6 inhibits cardiac hypertrophy by suppressing NFATc4 expression and activation." (PMID 37008337, 2023). "Loss of SIRT6 resulting in H3K9 acetylation increased, and by allowing c−Jun, a stress−responsive transcription factor to interact more easily, the IGF signaling was then increased, resulting in cardiac hypertrophy." (PMID 35958418, 2022). "In the cardiovascular system, SIRT6 plays a protective function by improving vascular endothelial dysfunction to some extent, delaying the formation of atherosclerotic plaques and inhibiting cardiac hypertrophy and heart failure." (PMID 33855020, 2021). "Inhibition of USP10 exacerbated cardiac hypertrophy by regulating sirtuin 6 (Sirt6) signaling." (PMID 34957094, 2021). "Finally, SIRT6 prevents cardiac hypertrophy, by inhibiting the IGF-AKT pathway and the NF-κB-dependent transcriptional activity." (PMID 33806509, 2021). "Reports have confirmed that SIRT6 plays a negative regulatory role in cardiac hypertrophy." (PMID 33855020, 2021). "Moreover, pharmacological inhibition of mTOR restored cardiac function in muscle-specific SIRT6 knockout mice, which spontaneously develop cardiac hypertrophy." (PMID 31372634, 2019). "Since SIRT6 is downregulated during cardiac hypertrophy, we tested whether overexpression of SIRT6 can reduce the augmented cardiac protein synthesis induced by hypertrophic agonist phenylephrine." (PMID 31372634, 2019).
cardiac hypertrophy (continued). "Thus, the cardioprotective effect of SIRT6 in an isoproterenol (ISO)-stimulated cardiac hypertrophy model appears to be dependent on the induction of autophagy." (PMID 31492861, 2019). "The decrease in deacetylase activity of SIRT6 might contribute to the development of cardiac hypertrophy." (PMID 30670969, 2018). "From the data currently available, it would seem that Nmnat2 manipulation, IGF signaling modulation and cellular autophagy targeting may be useful in targeting SIRT6 for future drugs in order to treat cardiac hypertrophy." (PMID 29966233, 2018). "In addition, cardiac-specific deletion of Sirt6 significantly increased left ventricular wall thickness, interstitial fibrosis and cardiomyocyte cross-sectional area, whereas overexpression of Sirt6 alleviates pressure-overload-induced cardiac hypertrophy and cardiac abnormalities." (PMID 36465178, 2022). "SIRT6 could reduce cardiac hypertrophy and cardiomyocyte senescence." (PMID 35463332, 2022). "Moreover, cardiac hypertrophy is reportedly observed in SIRT6-knockout mice." (PMID 35745840, 2022). "Besides, in the hypertrophic heart induced by ISO, the expression of SIRT6 was down-regulated, while the inhibition of mTOR restored cardiac function in muscle-specific SIRT6 knockout mice, which spontaneously developed into cardiac hypertrophy." (PMID 33855020, 2021). "In addition, SIRT2 and SIRT6 have emerged as prominent cardioprotective SIRTs, as deficiency of SIRT2 intensified cardiac hypertrophy in aged mice and mice stressed with angiotensin II, while a loss of SIRT6 in mice resulted in the development of cardiac hypertrophy and HF." (PMID 32486488, 2020). "Therefore, it becomes reasonable to conclude that the activation of SIRT6 in Ang-II induced hypertrophy may have been related to Nmnat2 expression and SIRT6, which, in this case, acts as a negative regulator in the case of cardiac hypertrophy." (PMID 29966233, 2018). "Furthermore, SIRT6 is downregulated in myocardial samples from heart failure patients and in mouse models of cardiac hypertrophy, and SIRT6 overexpression protects the heart from the effects of hypertrophic stimuli, which is consistent with our present findings." (PMID 28659816, 2017). "In the heart, SIRT6 binds to and represses the promoter of IGF signaling–related genes, thereby acting as a negative regulator of cardiac hypertrophy." (PMID 36901738, 2023). "However, it is notable that most of these experiments which are indicative of positive roles of Sirt6 in cardiac hypertrophy were conducted using primary rat cardiomyocytes, whether Sirt6 exerts a similar effect on other types of cell models deserves further inquiry." (PMID 37497437, 2023). "This was further confirmed by another paper which declared that Sirt6 directly inhibits IGF signaling cascade, slowing down the pathogenesis of cardiac hypertrophy." (PMID 37497437, 2023). "Studies on the hearts of mice confirmed that SIRT6 inhibits the activation of the IGF-Akt signal by inhibiting c-Jun transcriptional activity and deacetylation in H3K9, thereby blocking cardiac hypertrophy." (PMID 33855020, 2021). "SIRT6 and SIRT7 were critical for heart development and repress cardiac hypertrophy via modulating histone acetylation and transcription factors." (PMID 33611744, 2021). "In the model of hypertrophic cardiomyocytes induced by angiotensin II and coarctation of the abdominal aorta, SIRT6 inhibits the transcriptional activity of NF-κB by deacetylating H3K9, thereby inhibiting cardiac hypertrophy." (PMID 33855020, 2021). "Nonetheless, SIRT6 knocked-out mice promotes the over-activation of multiple IGF signal-related genes, leading to cardiac hypertrophy and heart failure." (PMID 33855020, 2021). "Few studies found that failing hearts of humans and mice showed decreased levels of Sirt6, suggesting that low levels of Sirt6 increase the activity of IGF-Akt, leading to initiation and progression of cardiac hypertrophy and heart failure." (PMID 33442387, 2020).
cardiac hypertrophy (continued). "In this particular study, it is shown that SIRT6 directly inhibits IGF signaling and inhibition of IGF signaling leads to a reduced rate of cardiac hypertrophy and vice versa." (PMID 29966233, 2018). "We firstly evaluated the effects of Ang II infusion on cardiac SIRT6 and ACE2 expression and myocardial hypertrophy." (PMID 29069788, 2017). "SIRT6 is a negative regulator of the myocardial IGF-Akt signaling pathway, the constitutive activation of which leads to cardiac hypertrophy." (PMID 28659816, 2017). "SIRT6 negatively controls insulin-like factor (IGF)/Akt signaling at the level of chromatin and culminates in the development of cardiac hypertrophy and heart failure in mice." (PMID 26732053, 2016). "Under pathological stress, reduced Sirt6 expression undermines H3K9 deacetylation, which in turn promotes binding of transcription factor c-Jun; the activation of downstream IGF-Akt signaling pathway results in cardiac hypertrophy." (PMID 37497437, 2023). "Many researchers argued that Sirt6 is a negative modulator in the progression of cardiac hypertrophy and heart failure." (PMID 37497437, 2023). "Similarly, SIRT6 downregulated the expression of NFATc4 and deacetylated NFATc4 to promote its nuclear export, thereby reducing BNP expression and protecting against cardiac hypertrophy." (PMID 36465178, 2022). "Indeed, SIRT6 serves as a negative regulator of IGF-Akt signaling, whose constitutive activation ultimately contributes to cardiac hypertrophy." (PMID 36465178, 2022). "SIRT6 knockout mice have cardiac hypertrophy and heart failure, while SIRT6 transgenic mice are not influenced by hypertrophy." (PMID 33855020, 2021). "Thus, SIRT6 inhibits the IGF/AKT pathway, which reduces the development of cardiac hypertrophy." (PMID 33806509, 2021). "The decrease of SIRT6 deacetylase activity in response to pressure overload or hypertrophic stimuli such as angiotensin II, isoprenaline and PE contributes to the pathogenesis of cardiac hypertrophy, although its expression is not altered." (PMID 30670969, 2018).